SPP1 (secreted phosphoprotein 1)
Diseases named in the same sentence as SPP1 in open-access papers (continued):
Sharing a sentence is not in itself a finding about the gene and the disease.
lung carcinoma (continued). "According to reports, SPP1 can promote tumor cell survival, regulate tumor-related angiogenesis and inflammatory responses, closely related to lung cancer, ovarian cancer, colon cancer, head and neck squamous cancer and adverse prognosis closely related." (PMID 35174205, 2022). "Previous studies suggested SPP1 itself can affect the proliferation and migration of tumor cells in lung cancer and colorectal cancer, however, its role in ESCA is less studied." (PMID 35593388, 2022). "It showed that high-expressed SPP1 is related to tumor staging, lymph node invasion, and tumor growth in lung carcinoma." (PMID 36585688, 2022). "In this study, TAM-derived SPP1 contributed to the chemo-resistance of lung cancer cell lines, and it additionally promoted re-growth after chemotherapy." (PMID 36139536, 2022). "In line with our findings, others have shown that the expression of SPP1 was elevated in a variety of cancerous tissues compared to normal tissues (GC, lung cancer, hepatocellular carcinoma, etc.)." (PMID 36612160, 2022). "SPP1 promotes the migration, invasion and cisplatin resistance of lung cancer cells, and overexpression of SPP1 is correlated with tumor grade and poor clinical prognosis." (PMID 36038839, 2022). "In lung cancer, SPP1 enhanced PD-L1 expression and mediated macrophage polarization to facilitate immune escape." (PMID 35037689, 2022). "Macrophages with high expression of SPP1 were also found to be one of the common phenotypes in lung cancer." (PMID 35874770, 2022). "We observed an enhancement of cell migration and invasive behavior in lung cancer cells induced after SPP1 treatment." (PMID 34676217, 2021). "Taken together, the high expression of SPP1 in lung cancer tissues was partly regulated by the reduced DNA methylation in its promoter region." (PMID 33996808, 2021). "We next analyzed the correlation between the high expression of SPP1 and the prognosis of patients with lung cancer." (PMID 33996808, 2021). "In the present study, we employed TCGA analysis and identified SPP1 (isoform 5) as a cancer-promoting gene that contributes to poor prognosis, cancer progression and cisplatin-resistance of lung cancer." (PMID 33996808, 2021). "In this study, we set force to verify the specific role of SPP1 in regulating lung cancer resistance and lung cancer cell progression." (PMID 33996808, 2021). "The import role of SPP1 in regulating the proliferation, migration, invasion and cancer resistance of lung cancer was validated in our study." (PMID 33996808, 2021). "Our study demonstrated that abnormally high levels of SPP1 were present in patients with ALK-positive lung cancers, similar to previous findings in pediatric patients with ALK-positive anaplastic large cell." (PMID 34234236, 2021). "We showed that SPP1 promoted the proliferation, migration and invasion of lung cancer cells, and increased the resistance of lung cancer to the chemotherapeutic drug cisplatin." (PMID 33996808, 2021). "To investigate the regulatory mechanism of SPP1, we performed TCGA analysis to compare the methylation levels of the promoter of SPP1 in lung cancer tissues and normal tissues." (PMID 33996808, 2021). "Immunohistochemical staining showed that SPP1 staining pattern in lung cancer was cytoplasmic, and the average scores for 5 ALK-positive and 5 ALK-negative lung cancer samples were 6.8 ± 1.095 and 0.8 ± 0.837, respectively." (PMID 34234236, 2021). "Significant overexpression of SPP1 protein in ALK-positive lung cancer was confirmed by IHC compared to paired adjacent normal tissues and ALK-negative cancers." (PMID 34234236, 2021). "In conclusion, here we have demonstrated that SPP1 is a cancer-promoting gene involved in lung cancer proliferation, migration, invasion and cisplatin resistance." (PMID 33996808, 2021).
lung carcinoma (continued). "Here using TCGA analysis, we showed that lung cancer tissues were characteristic of hypomethylation in the promoter region of SPP1, which potentially contributed to the dysregulation of the SPP1 gene." (PMID 33996808, 2021). "Excitingly, our finding revealed a dramatical increase of SPP1 mRNA (35.954-fold) in ALK-positive lung cancers using NanoString analysis and then overexpression of SPP1 protein was confirmed by IHC." (PMID 34234236, 2021). "We showed that SPP1 was the most pronouncedly upregulated gene in lung cancer, and patients with high SPP1 expression demonstrated significantly poorer overall survival and first progression." (PMID 33996808, 2021). "TMA analysis of 159 lung cancer tissue samples demonstrated that MVD was increased in patients with positive expression of SPP1 in TAMs compared with that in the SPP1-negative group." (PMID 33194645, 2020). "Patients who had a high expression of SPP1 showed poor prognosis in melanoma and in blood, brain, breast, colorectal, and lung cancer (p < 0.05)." (PMID 31849319, 2019). "By IHC assay, we found that Cd68 positive macrophages were also strongly stained by Spp1, whereas Ttf1-positive lung cancer cells were only weakly stained positive for Spp1." (PMID 26565418, 2015). "Ongoing research has discovered that SPP1 in MPE due to lung cancer has numerous effects: it progresses the tumor both in its growing and metastasis, and prolongs the survival of cancer cells." (PMID 24758329, 2014). "Most samples from colon adenocarcinoma, breast adenocarcinoma, ovary adenocarcinoma, and lung cancer showed intermediate to strong cytoplasmic SPP1 staining in tumor cells, but the staining in normal tissues was much weaker." (PMID 17989776, 2007). "Several studies in lung cancer used OPN/Spp1 as a marker for TAM subpopulation classification." (PMID 40865052, 2025). "In lung cancer, SPP1+ TAMs stand at the crossroads of fibrosis, metabolism, and immune regulation." (PMID 40395129, 2025). "One mechanism by which SPP1 promotes lung cancer metastasis involves COL11A1-mediated EMT." (PMID 40559389, 2025). "Genes KRT81, SPP1, PCDH7, SLC2A1, and TET1 were significantly upregulated in tumor tissues and associated with poor prognosis and survival, providing insights for exploring lung cancer biomarkers in future studies." (PMID 41415280, 2025). "Based on in vitro experiments, the inhibition of SPP1 in THP-1 differentiated macrophages co-cultured with the A549 cell line can mitigate lung cancer progression in the cell line model and restore T cell activation, showing the potential of targeting SPP1 in various cancers." (PMID 39691723, 2024). "Previous study demonstrated that upregulated SPP1 contributes to cell proliferation, migration and invasion of lung cancer and is relates to cisplatin resistance, whereas inhibition of SPP1 may improve the survival." (PMID 38466483, 2024). "For instance, the SPP1 gene encoding the secreted phosphoprotein 1, an extracellular matrix (ECM) protein with several adhesion receptor binding domains, is associated with lung cancer progression, resistance to therapy and poor prognosis." (PMID 39766023, 2024). "Several reports have discussed SPP1 in serum or plasma of lung cancer patients." (PMID 37190178, 2023). "Patients with overexpressed SPP1 in lung cancer presented a poor prognosis." (PMID 38204755, 2023). "Several reports have discussed SPP1 expression on cancer cells in lung cancer patients." (PMID 37190178, 2023). "In this review, we mainly discussed the function and significance of SPP1 derived from TAMs in lung cancer, but differences might exist between each organ and histological subtype." (PMID 37190178, 2023). "SPP1 enhances the drug resistance of the second generation EGFR TKI in lung cancer treatment." (PMID 36688087, 2023).
lung carcinoma (continued). "Notably, elevated expression levels of production of immunoglobulin-related genes IGHG4, IGKC, IGLC2, IGHG3, and PLAU were detected in the SPP1-Mφ cluster, suggesting the proinflammatory and anti-tumor functions of this cluster in lung cancer." (PMID 36008393, 2022). "Patients with high SPP1 overexpression have a poor prognosis in lung cancer." (PMID 36266702, 2022). "Moreover, SPP1 has been demonstrated to be significantly overexpressed in afatinib-resistant lung cancer cells, and that the knockdown of SPP1 increases the chemotherapy sensitivity of lung cancer cells." (PMID 35865173, 2022). "SPP1 is also considered as a marker for highly malignant lung cancer." (PMID 36518809, 2022). "Moreover, SPP1 plays a crucial role in EMT and SPP1 overexpression levels have also been associated with metastasis of lung cancers, colorectal cancers and melanomas." (PMID 34234236, 2021). "With the advance of siRNA delivery technologies, the development of the SPP1 silencing strategy could be a potential approach to improve the prognosis of lung cancer patients." (PMID 33996808, 2021). "For the first time, we revealed that SPP1 overexpression is associated with poor outcomes in ALK fusion lung cancer patients who did not receive targeted therapy." (PMID 34234236, 2021). "To further confirm this phenomenon, we analyzed the lung cancer patient data in the GEO database and found that patients with higher expression of SPP1 had poorer overall survival rate, and patients with higher expression of SPP1 also had poorer first progression." (PMID 33996808, 2021). "We hypothesized that ALK-positive lung cancer cells augment the activity of bone resorption via promoting the differentiation of osteoclasts by secreting SPP1 and lead to osteolytic bone metastasis." (PMID 34234236, 2021). "Therefore, we found a significant upregulation of SPP1 expression in ALK-positive lung cancers compared to ALK-negative lung cancers and paired adjacent normal tissues (P < 0.0001)." (PMID 34234236, 2021). "In addition, SPP1 has been reported to be involved in many aspects of head and neck cancer, lung cancer and gastric cancer." (PMID 34404882, 2021). "SPP1 (isoform 5) upregulation showed the most pronounced upregulation in lung cancer tissues." (PMID 33996808, 2021). "We next explored the function of SPP1 in lung cancer at the cellular level." (PMID 33996808, 2021). "SPP1 expression is closely related to immunity in lung cancer, ediates the polarization of macrophages, and promotes the immune escape of lung adenocarcinoma via upregulation of PD-L1, leading to the metastasis of lung cancer cells." (PMID 34122521, 2021). "SPP1 expression was previously found to be up-regulated in lung cancer tissues." (PMID 34308964, 2021). "We next investigated the role of SPP1 in the resistance to chemotherapy for lung cancer." (PMID 33996808, 2021). "Further, as a mechanistic study, we hypothesized that DNA methylation was responsible for regulating the expression of SPP1 in lung cancer." (PMID 33996808, 2021). "Meanwhile, SPP1 mediating macrophage polarization leads to upregulation of PD-L1 and facilitates immune escape in lung adenocarcinoma, which also suggests a potential therapeutic target for lung cancer." (PMID 33968738, 2021). "Together, these data suggested that SPP1 promoted cisplatin resistance in lung cancer, and targeting SPP1 might be a potential treatment strategy to overcome resistance." (PMID 33996808, 2021). "It was reported that SPP1 could not only be used as a prognostic biomarker of lung cancer but also play a role in mediating macrophage polarization and immune escape." (PMID 32699529, 2020). "It has been noted that the expression of SPP1 is high in numerous tumors, including lung cancer." (PMID 24758329, 2014).
lung carcinoma (continued). "SPP1, also known as osteopontin, is expressed by various cell types, including tumour‐associated macrophages, and its high expression on TAMs often indicates negative prognosis and chemoresistance in lung cancer." (PMID 39601163, 2024). "Notably, elevated SPP1 is also observed in colon, gastric, and lung cancers." (PMID 39596132, 2024). "Furthermore, recent findings reported that SPP1 could mediate the immune response and influence immunotherapy response in lung cancer through the modulation of macrophage M2 polarization and PD-L1 expression." (PMID 38067407, 2023). "In addition, SPP1 is also considered a marker of early lymphatic metastasis in lung cancer." (PMID 36688087, 2023). "Therefore, we analyzed the expression of SPP1 in lung cancer and different cancers." (PMID 36688087, 2023). "In addition, SPP1 is a potential marker for identifying monocyte-derived TAMs in lung cancer." (PMID 36139536, 2022). "Furthermore, SPP1 contributed to anti-cancer drug resistance in lung cancer cell lines." (PMID 36139536, 2022). "Our results may be explained by the fact that TAM-derived SPP1 induces BMI1 in lung cancer cells." (PMID 36139536, 2022). "However, the role of SPP1 in lung cancer is yet to be clarified." (PMID 33996808, 2021). "On the other hand, knockdown of SPP1 using siRNAs effectively restored the sensitivity of A549 cells to cisplatin treatment, which suggests that silencing SPP1 could be a viable means to increase the sensitivity of lung cancer to cisplatin treatment." (PMID 33996808, 2021). "Further, SPP1 expression was significantly higher in lung cancer tissues than in normal tissues, and the expression of SPP1 in young patients was also significantly higher than that in older patients, which indicated that SPP1 might be related to the rejuvenation of lung cancer." (PMID 33996808, 2021). "Previous studies found that SPP1 played a role in lung cancer escape and mediating macrophage polarization, while inhibiting SPP1 expression might overcome resistance to second-generation epidermal growth factor receptor gene (EGFR)–tyrosine kinase inhibitors (TKIs)." (PMID 33681226, 2021). "SPP1 enhanced the second-generation epidermal growth factor receptor (EGFR) tyrosine kinase inhibitor (TKI) resistance in lung cancer, which offered a new scheme for targeted therapy that inhibiting SPP1 might be a therapeutic target to overcome afatinib resistance." (PMID 33968738, 2021). "Also, the recent study showed that SPP1 could mediate macrophage polarization and lung cancer evasion, which could be used as a promising drug target (Zhang, Du, Chen, & Xiang, 2017)." (PMID 30746900, 2019). "SPP1+ macrophages have been identified in the lungs of individuals with COVID-19, IPF, and lung carcinoma and in BAL fluids from TB and latent TB patients." (PMID 41489684, 2026). "We characterized the TMEs in LM and BM, revealing that the LM of lung cancer is a “cold tumor”, featuring minimal plasma cells, dendritic cells, pro-inflammatory macrophages, and CD8+ T effector cells, along with increased SPP1 positive myeloid cells." (PMID 40883281, 2025). "Interestingly, FN1+SPP1+ monocyte-derived macrophages are believed to be involved in the pathogenesis of canine idiopathic pulmonary fibrosis and profibrotic SPP1+ monocyte-derived macrophages were also reported in human COVID-19, pulmonary fibrosis and lung cancer." (PMID 40114924, 2025). "We confirmed that CD44 and ITGB1 are PI4K2A-associated proteins and that SPP1 binds to CD44 and ITGB1 in mesenchymal lung cancer cells." (PMID 36757799, 2023). "qRT-PCR and immunohistochemistry indicated that several key molecules such as Osteopontin/Spp1, Hmox1, Mmp12, and ERBB2 were markedly altered and/or localized in the preneoplastic lesions, suggesting their participation in the induction of lung cancer." (PMID 37513116, 2023).
lung carcinoma (continued). "Firstly, scRNA-seq study described a cellular module termed Lung Cancer Activation Module (LCAM), which was composed of PDCD1+CXCL13+ activated T cells, IgG+ plasma cells, and SPP1+ macrophages." (PMID 37187731, 2023). "It has been proven that the SPP1 gene (OPN) can inhibit the autophagy and apoptosis of cells, leading to the development of lung cancer cells and promoting cancer cell proliferation." (PMID 37623509, 2023). "have revealed that SPP1+ macrophages and PDCD1+CXCL13+ activated T cells were correlated with the activation of lung cancer, indicating their essential role in cancer progression." (PMID 37846760, 2023). "The results showed that SPP1, SLC2A1 was significantly highly expressed in the lung cancer cell, while AGER was in the opposite." (PMID 36782138, 2023). "High SPP1 expression was observed in TAMs and tumor tissues with advanced TNM stages in lung carcinomas." (PMID 36148946, 2022). "We discovered that EV uptake increase the expression of SPP1, CD44, and POSTN genes in lung cancer cells." (PMID 36424413, 2022). "SPP1 was more highly expressed in macrophages and THP-1 (a monocyte-like cell line) than in the lung cancer cell lines." (PMID 36139536, 2022). "Based on transcript level expression study using quantitative real-time PCR showed five significantly differentially expressed genes SPP1, VEGFA, CD44, FOXO1 and POSTN in EVs cargo derived from lung cancer patients with bone metastasis." (PMID 36424413, 2022). "Thus, targeting SPP1 may be an attractive therapeutic approach for aggressive lung cancer." (PMID 34234236, 2021). "Deregulation of PI3K/AKT signaling pathway in ALK-positive lung cancer was demonstrated by WES analysis, and significantly increased mRNA of ALK, ROS1, MET, SPP1 and PI3K signaling pathway was identified by NanoString assay." (PMID 34234236, 2021). "Suppression of SPP1 expression, either through siRNA or DNMT1 overexpression, is a potentially novel approach to inhibit the progression of lung cancer." (PMID 33996808, 2021). "Thus we concluded that SPP1 overexpression is associated with poor outcomes for patients with ALK fusion lung cancer without receiving targeted therapy and PI3K/AKT/SPP1 pathway may become the promising targets in patients with aggressive lung cancer." (PMID 34234236, 2021). "We prioritized SPP1 as a TAM-secreted factor to act on cancer cells and found a significant enhanced migration phenotype and invasion ability in A549 lung cancer cells induced by recombinant protein SPP1." (PMID 34676217, 2021). "The obvious increase of SPP1 mRNA and protein in ALK-positive lung cancers is attracting considerable interest." (PMID 34234236, 2021). "SPP1 is progressively up‐regulated in the lungs of patients with COPD, lung cancer (LC) and LC coexisting with COPD, as shown by bioinformatic analysis." (PMID 33626243, 2021). "We found significant expression of SPP1, OCT4A, and OCT4Bv transcripts in MDA-MB-231, HEC50B, and A549 (cancer cell lines) and in HCC827 GRH2 and HCC827 ARH (drug-resistant lung cancer cell lines)." (PMID 32503462, 2020). "SPP1 binds to CD44 and integrin receptor in the lung cancer cell and activates the FAK/PI3K/AKT pathway which induces the secretion of vascular endothelial growth factor (VEGF) resulting in increased cell survival, cell proliferation and tumor metastasis." (PMID 31681566, 2019). "SPP1, AGER, and RTKN2 regulate the lung cancer-related pathways such as VEGF (vascular endothelial growth factor) signaling pathway and NF-kappaB." (PMID 30453959, 2018). "In the case study in lung cancer the general conclusions are: RAGE and SPP1 showed large change between controls and cancer." (PMID 26471143, 2015). "SPP1 activated β-catenin by facilitating its translocation to the nucleus and promoted an EMT, leading to the progression of lung cancer." (PMID 26565418, 2015).